RNU6-659P (RNA, U6 small nuclear 659, pseudogene)
Gene: Small nuclear RNA gene on chromosome 14 (70,496,107 to 70,496,210, forward strand). Ensembl gene ENSG00000252263.
Homologues: Orthologues: chimpanzee U6 (100% identical), macaque U6 (94% identical), rat U6 (83% identical), pig U6 (81% identical), guinea pig U6 (72% identical). Paralogues in human: RNU6-936P (88% identical), RNU6-211P (87% identical), RNU6-21P (87% identical), RNU6-144P (86% identical), RNU6-15P (86% identical), RNU6-723P (86% identical), RNU6-1152P (85% identical), RNU6-1263P (85% identical), RNU6-16P (85% identical), RNU6-31P (85% identical), RNU6-333P (85% identical), RNU6-417P (85% identical), and 1287 more.